MIR610 (microRNA 610)
Synonyms: hsa-mir-610; MIRN610
Gene: MicroRNA gene on chromosome 11 (28,056,815 to 28,056,910, forward strand). Ensembl gene ENSG00000207874.
Homologues: Orthologues: chimpanzee ptr-mir-610 (100% identical).